INS (insulin)
Diseases named in the same sentence as INS in open-access papers (continued):
Sharing a sentence is not in itself a finding about the gene and the disease.
diabetes (continued). "On the Takashi2019 diabetes type 1 dataset, the key variables for the prediction of past diabetes duration resulted being age, daily bolus dose of insulin, and gait speed." (PMID 38435625, 2024). "Multiple linear regression analysis further showed that the peak C-peptide along with peak glucose affected the iAUC 30-180 glucagon after adjusted for sex, age, BMI, duration of diabetes, and daily insulin dose (R2 = 0·335, P = 0·033)." (PMID 39149119, 2024). "In diabetes-prone mice, Camp enhances glucose-stimulated insulin secretion and modulates inflammatory responses, reducing β-cell apoptosis." (PMID 39728453, 2024). "There was also evidence that FABP4 has a significant influence on lipid metabolism by altering the classic lipid profile which is mediated by insulin resistance, particularly in patients with diabetes." (PMID 38731797, 2024). "GCKR, influencing glucose metabolism, has variations associated with diabetes risk, while PPARG plays a pivotal role in adipogenesis and insulin sensitivity, highlighting its importance in T2DM37,38." (PMID 39020091, 2024). "Adiponectin, an adipose cell-synthesized hormone, regulates insulin sensitivity and has functions in obesity, diabetes, inflammation, atherosclerosis, and cardiovascular disease." (PMID 38736904, 2024). "Diabetes mellitus (DM) is a group of physiological disabilities characterized by hyperglycemia resulting from insulin resistance, insufficient insulin excretion, or elevated glucagon excretion." (PMID 39590327, 2024). "Earlier studies have shown that insulin treatment ameliorates impaired corneal re-epithelialization in diabetic rats, and that topical application of insulin in rats with type 1 diabetes mellitus normalizes corneal wound-healing." (PMID 39062510, 2024). "Significant prognostic factors of any retinopathy were longer duration of diabetes, higher fasting serum glucose, use of diabetic oral medication or insulin, and greater waist–hip ratio." (PMID 38694495, 2024). "The relationship between sarcopenia and insulin resistance suggests insulin therapy’s potential in preserving muscle mass, particularly in Type 2 diabetes mellitus (T2DM) patients." (PMID 39058051, 2024). "For diabetes treatment, insulin is typically delivered subcutaneously through cannula-based syringes, pens, or pumps in almost all type 1 diabetic (T1D) patients and some type 2 diabetic (T2D) patients." (PMID 38509342, 2024). "A growing amount of research shows that both insulin resistance and the direct toxic effects of iron on pancreatic beta cells and their insulin secretory ability are both involved in the development of diabetes mellitus with β-TM." (PMID 38575692, 2024). "Mediation analysis showed that white blood cells strongly influenced the correlations between diabetes-related indicators (glycohemoglobin, fasting glucose, and insulin) and OAB." (PMID 38745959, 2024). "Several DAWN2 transnational studies have also found that diabetes brought psychological burden to patients with diabetes, which were likely to be one of the reasons that hinder insulin treatment." (PMID 39036047, 2024). "Due to the severity of diabetes, insulin therapy is typically required for treating patients with FPLD." (PMID 39398333, 2024). "While the decline in insulin production and secretion was previously attributed to apoptosis of insulin-producing β-cells, recent studies indicate that β-cell apoptosis rates are relatively low in diabetes." (PMID 38915897, 2024). "Diabetes is a chronic metabolic disease characterized by elevated blood glucose levels due to insufficient insulin secretion or impaired insulin action." (PMID 38954714, 2024). "Nutmeg demonstrates antidiabetic effects by enhancing insulin sensitivity, regulating blood glucose levels, and exhibiting antioxidant properties that protect against oxidative stress in diabetes." (PMID 39519546, 2024).
diabetes (continued). "The insulin/IGF-1 axis has emerged as a pivotal mediator in the connection between obesity and the risk of diabetes." (PMID 38375323, 2024). "A cross-sectional retrospective study in South Korea concluded that patients with early-onset T2D were characterized by higher blood glucose levels, more family history of diabetes, early-onset of microalbuminuria, and insulin therapy as initial treatment." (PMID 38529395, 2024). "Every theoretical framework provides a distinct solution to the fundamental limits of conventional insulin treatments for a more effective, adaptable, and patient-focused approach to managing diabetes." (PMID 38542928, 2024). "Characterized by a progressive loss of insulin secretion due to insulin resistance, T2DM is known as the leading cause of death and disability worldwide, mainly due to diabetes-related complications." (PMID 39687000, 2024). "Insulin plays a critical role in glucose metabolism and is often used to manage hyperglycemia in patients with diabetes, which is a common comorbidity in cardiometabolic disorders." (PMID 39598569, 2024). "The pathophysiology that links diabetes and cardiovascular complaints is endothelial cell dysfunction induced by hyperglycemia, excess free fatty acid release, and insulin resistance." (PMID 38637769, 2024). "Glucose and insulin metabolism are significantly altered in patients with diabetes who have advanced chronic kidney disease (CKD)." (PMID 38435391, 2024). "In a retrospective analysis of the Malaysian primary care-based National Diabetes Registry, among non-insulin-treated patients with T2D and HbA1c ≥8% (64 mmol/mol), 54% had delayed treatment intensification with a median time of 13 months." (PMID 38166049, 2024). "Type 2 diabetes mellitus (T2DM) is the most common type of diabetes and occurs due to insufficient insulin secretion or inability to use existing insulin and the effects of environmental factors." (PMID 39051061, 2024). "A major consequence of obesity is a disruption to glucose and insulin metabolisms, leading to metabolic conditions including insulin resistance and/or diabetes." (PMID 38473112, 2024). "Insulin plays a critical role in the regulation of glucose metabolism and the maintenance of glucose homeostasis making it a cornerstone in the treatment of diabetes." (PMID 39188698, 2024). "Terpenes are known for their beneficial effects on the treatment of diabetes, like the stimulation of insulin release (stevioside), anti-hyperglycemic activity (tinosporaside) or increase of glucose uptake (palbinone) (reviewed in41)." (PMID 39739113, 2024). "Insulin resistance is a major pathophysiological feature of type 2 diabetes mellitus, characterized by a decreasing ability of insulin to regulate glucose metabolism." (PMID 39430786, 2024). "Diabetes mellitus (DM), a condition characterized by hyperglycemia due to insulin underproduction and/or insulin resistance, has been documented for millennia." (PMID 39766270, 2024). "It predominantly manifests in females and rarely in males, particularly those who have diabetes and are undergoing insulin treatment." (PMID 39220553, 2024). "Insulin is required for the survival of people with type 1 diabetes and for the enhanced control of diabetes in some patients with type 2 diabetes." (PMID 38584277, 2024). "Conventional insulin requires strict adherence to timing, reducing patients' ability to manage diabetes in their daily lives." (PMID 39734941, 2024). "Among those with known diabetes, there was a significant interaction between the prudent pattern, the traditional pattern, and insulin use in relation to poor glycemic control." (PMID 39064637, 2024). "The monitoring of blood glucose and proper insulin dosage was a crucial part of diabetes management, hence the doctors were dependent solely on the patients reporting their blood glucose levels accurately and in determining their next doses." (PMID 39080764, 2024).
diabetes (continued). "Diabetes mellitus (DM) is a common chronic metabolic disorder characterized by elevated blood glucose levels, arising from either insufficient insulin production or impairments in insulin signaling." (PMID 39598390, 2024). "The patient had a 10-year history of hypertension, controlled with oral ACE inhibitors, and a 20-year history of diabetes, managed with insulin." (PMID 39777334, 2024). "The widespread use of insulin and varying types, notably glargine and aspart, is consistent with current pediatric diabetes management guidelines emphasizing the importance of insulin therapy." (PMID 38590482, 2024). "The fasting insulin test measures the level of insulin in the blood after a period of fasting and can indicate a trend toward diabetes." (PMID 38481895, 2024). "At recruitment, endogenous insulin levels were significant, but insulin treatment was required after 10 years of diabetes in 69% of patients." (PMID 39201476, 2024). "Although new glucose-responsive insulin delivery systems have been developed in recent years, how to more effectively control blood sugar and prevent or treat complications of diabetes remains a key issue in current research." (PMID 39055304, 2024). "Fecal transplants even show promise in altering gut microbiota and potentially preserving insulin production in newly diagnosed diabetics." (PMID 39435211, 2024). "The enhancement of insulin secretion and of the proliferation of pancreatic β cells are promising therapeutic options for diabetes." (PMID 37945752, 2024). "The Centre for Disease Control reports that 5.8% of all United States adults (over the age of 20 years) diagnosed with diabetes had both a diagnosis of T1D and were using insulin." (PMID 39060948, 2024). "Previous studies have reported that the research on plant secondary metabolites for diabetes mainly focuses on regulating lipid and protein metabolism pathways, insulin signaling pathways, anti-inflammatory responses, and anti-oxidant stress." (PMID 39045049, 2024). "Diabetes mellitus is a group of metabolic diseases characterized by chronically elevated blood glucose levels as a result of defects in insulin secretion, insulin action or both." (PMID 38778408, 2024). "Last, we demonstrate the efficacy of our anti-windup designs using three numerical simulations, including an FDA-approved model for glucose-insulin response in patients with diabetes (type I)." (PMID 39167660, 2024). "Type 1 diabetes mellitus is a medical condition that is characterized by a decrease in insulin level and an increase in glucose concentration in the body." (PMID 38785837, 2024). "This technique cansupport careful testing on single β-cell function and unlockmechanistic information about diabetes drugs, for example, their effecton the fusion pore and varying insulin secretion yield." (PMID 39713028, 2024). "In type 1 diabetes mellitus, the destruction of β cells leads to the cessation of insulin production, and C-peptide levels become undetectable." (PMID 39432712, 2024). "The financial cost of maintaining basic survival for people with T1D is excessively high and is leading to rationing of insulin and diabetes supplies for many." (PMID 38711747, 2024). "For example, very few private plans cover the cost of medications, and the SUS provides free essential diabetes medications, including insulin, at clinics and through private pharmacies." (PMID 38792326, 2024). "They offer potential therapeutic benefits in managing MetS and diabetes by enhancing insulin sensitivity, correcting glucose intolerance, normalizing lipid profiles, and reducing hypertension." (PMID 38934020, 2024). "Information on escalation of diabetes management in terms of insulin therapy can increase the understanding of health care utilization due to poor glycemic control over disease duration and time." (PMID 39020360, 2024).
diabetes (continued). "7S,14R-diHDHA promoted MSC paracrine functions in db/db mice in vivo to ameliorate diabetic mellitus through improving β-cell function, lowering blood sugar, improving glucose tolerance, and increasing blood insulin levels." (PMID 38533089, 2024). "In model 2, after adjusting for the use of multiple medications including anti-diabetes, insulin, antihypertensive, and lipid-lowering medications, the association between FG and incident SMI was attenuated." (PMID 38637769, 2024). "SMBG data can be useful not only in confirming hypoglycemia or hyperglycemia in real time but also in the long-term management of diabetes (adjusting insulin, diet, and exercise)." (PMID 38241065, 2024). "Changes in blood values due to the development of pre-diabetes were seen in increased insulin levels in both hygiene groups." (PMID 39019114, 2024). "Despite advancements in diabetes management, including lifestyle modifications, oral hypoglycemic agents, and insulin therapy, the prevention and treatment of diabetes-related vascular complications remain significant challenges." (PMID 39030705, 2024). "The main subtypes of DM are type 1 diabetes Mellitus (T1DM) and type 2 diabetes mellitus (T2DM), which are characterized by failure in insulin production and relative insulin deficiency mediated by autoimmune and metabolic mechanisms, respectively." (PMID 38751366, 2024). "Type 1 diabetes mellitus (T1DM) is a common autoimmune pathology requiring lifelong insulin therapy." (PMID 39735069, 2024). "This population also suffers from co-morbidity and a greater number of diabetes related complications, such as visual and cognitive impairment, which can potentially affect their ability to manage insulin regimens." (PMID 38778253, 2024). "The findings of studies have demonstrated that the knowledge of school nurses in utilizing diabetes devices, such as glucose meters and insulin pumps, significantly impacts the quality of care provided to students with diabetes." (PMID 39221386, 2024). "Lipodystrophy syndromes should be considered when metabolic symptoms are disproportionate to body size, including diabetes with high insulin requirements, hypertriglyceridemia, fatty liver disease, or polycystic ovary syndrome (PCOS)." (PMID 38952397, 2024). "Despite advances in insulin pharmacology, delivery systems and glucose monitoring technologies, hypoglycaemia remains a substantial challenge for people with insulin-treated diabetes." (PMID 39080044, 2024). "Diabetes mellitus is a chronic metabolic disorder characterized by persistent hyperglycemia resulting from defects in insulin secretion, insulin action, or both." (PMID 38548784, 2024). "Our findings revealed a substantial reduction in insulin demands following MSC therapy in patients with diabetes, which was consistent across all included studies with follow-up periods of 3, 6, 9, and 12 months." (PMID 38800472, 2024). "Generally, diabetes management encompasses main approaches, including blood glucose reduction, protection of beta cells from dysfunction, and insulin action improvement." (PMID 38716357, 2024). "As for the treatment for diabetes control, 45% (n=22) of the participants were using oral antidiabetic drugs and 12% (n=6) of the participants were using insulin." (PMID 38754101, 2024). "Sedentary behavior (e.g. TV viewing) is associated with incident diabetes, CVDs, COPD, and total mortality partly through decreasing insulin sensitivity and blood circulation, promoting oxidative stress, and impairing vascular endothelial dilation." (PMID 39559882, 2024). "Type 1 diabetes mellitus was diagnosed based on the acute onset of osmotic symptoms with or without diabetic ketoacidosis (DKA), severe hyperglycemia (blood glucose >13.9 mmol/l (>250 mg/dl)), and insulin requirement from the onset of diabetes." (PMID 39006700, 2024).
diabetes (continued). "Concomitant medications especially diabetes medications showed biguanides (87.25%), sulfonylureas (41.18%), insulin (18.63%), and thiazolidinediones (9.80%)." (PMID 39246417, 2024). "Diabetes mellitus (DM) is a group of metabolic syndromes that are characterized by high blood glucose levels resulting from deficits in insulin-related pathways." (PMID 38890763, 2024). "T1D can be managed with exogenous insulin, and while technology surrounding glucose monitoring and insulin delivery have revolutionized diabetes care, effective disease management remains difficult, time-consuming, and costly." (PMID 38582818, 2024). "The included studies assessed vascularity, heart rate, lipids, insulin sensitivity, inflammatory markers, diabetes, and other relevant indicators." (PMID 38906965, 2024). "When secondary adrenal insufficiency owing to pituitary apoplexy occurs in patients with diabetes, increased sensitivity to insulin, hypoglycemia, or even complete amelioration of diabetes can occur." (PMID 39085948, 2024). "The majority of patients with diabetes mellitus will ultimately need insulin 8 to 10 years after the diagnosis of diabetes to maintain good glycaemic control." (PMID 39020348, 2024). "The defects in insulin resistance and insulin secretion most likely antedate pregnancy in many cases, especially in populations with high rates of diabetes and obesity." (PMID 39389786, 2024). "The glycemic efficacy of tirzepatide in the treatment of T2DM was found to be due to simultaneous improvements in key components of diabetes pathophysiology, including beta-cell function, insulin sensitivity, and glucagon secretion, in Phase 1 clinical trials." (PMID 39598478, 2024). "Diabetes is a chronic illness characterized by abnormalities in the action or secretion of insulin, or sometimes both." (PMID 39398666, 2024). "Diabetes mellitus is a metabolic disorder characterized by a reduction in insulin production by pancreatic islet cells, which consequently results in an elevated blood glucose level and abnormalities in the metabolism of carbohydrates, proteins, and lipids." (PMID 38167129, 2024). "Two of the SEARCH studies reported that PWV progression was associated with waist circumference, LDL‐C, HbA1c, age, duration of diabetes, smoking status, insulin sensitivity, and mean arterial blood pressure." (PMID 37853936, 2024). "Type 1 diabetes mellitus (T1DM) is a chronic autoimmune condition where the immune system attacks the insulin-producing beta cells in the pancreas, resulting in the body producing very little or no insulin." (PMID 39246901, 2024). "Compared to other medications (i.e., insulin, thiazolidinediones, SGLT2 inhibitors, and sulfonylurea), metformin demonstrated significantly improved outcomes in any diabetes-related endpoint, all-cause mortality, and stroke." (PMID 39310418, 2024). "While inflammation is beneficial for insulin secretion during homeostasis, its transformation adversely affects β cells and contributes to diabetes." (PMID 38885342, 2024). "This list can be further extended to cases of reduced insulin sensitivity up to poorly controlled insulin-dependent diabetes mellitus, where GH resistance has also been described." (PMID 38819617, 2024). "Streptozotocin (STZ) induced type I diabetes mellitus (DM) models have been pivotal in diabetes research due to their ability to mimic the insulin‐dependent hyperglycemia akin to human type‐I diabetes." (PMID 39350510, 2024). "It positively affects both insulin levels and insulin sensitivity, as well as glucose levels and diabetes symptoms." (PMID 39684343, 2024). "Patients within the RYGB group had a longer duration of diabetes, which correlated with a higher percentage of them requiring insulin, as well as a higher number of anti-diabetic medications." (PMID 38182725, 2024).